PIK3CA (phosphatidylinositol-4,5-bisphosphate 3-kinase catalytic subunit alpha)
Diseases named in the same sentence as PIK3CA in open-access papers (continued):
Sharing a sentence is not in itself a finding about the gene and the disease.
tumor (continued). "Firstly, IHC staining revealed that PIK3CA was strongly positive in TPMCa tumors, while PIK3R1 is negative in TPMR1 tumors, indicating that the tumor cells originate from a specific genotype of organoids." (PMID 37340596, 2023). "Second, the main tissues tested in this study for IHC were tumor tissues, and paraneoplastic tissues were not included to compare the differences of VEGF, IL-8, IL-10, PIK3CA, and RIP2." (PMID 36567775, 2022). "Moreover, a recent study also reported a remarkable response (73% tumor shrinkage) in an HNSCC patient with a noncanonical activating PIK3CA mutation who received alpelisib monotherapy, underscoring the need to further understand the noncanonical PIK3CA mutation biology." (PMID 35887235, 2022). "Knockout of p85β reduced cell proliferation, colony formation, and xenograft tumor growth of the DLD1 PIK3CA E545K-only cells, but not the WT PIK3CA-only counterpart." (PMID 35418124, 2022). "Other copy number reduced genes included SMAD4, HNF1B, and some gene loci that are not known to be tumor suppressor genes, such as KRAS, MYC, PIK3CA, and IL6." (PMID 36430324, 2022). "This means that gene PIK3CA does not directly regulate gene CREBBP in the normal state, and PIK3CA can affect the tumor gene CREBBP in the tumor state." (PMID 34335688, 2021). "However, as already mentioned, because RAS, PIK3CA and PTEN mutations are more associated with the metastatic process than primary tumor development, there may be the possibility of not detecting these mutations in primary tumor tissues." (PMID 32823871, 2020). "We used two human papilloma virus negative (HPV−)/PIK3CA-WT PDXs, #20 and #103, to explore how the combination of GDC0032 or BYL719 with abemaciclib will affect pathway inhibition and tumor viability." (PMID 33036331, 2020). "Consistent with this idea, we find that the expression levels of ETV4, ERG, PIK3CA, and RSPO3 were elevated ~ 80–800-, ~ 25-, ~ 8-, and ~ 10–30-fold compared to the fusion-negative group of the same tumor type, respectively." (PMID 32631391, 2020). "Although RICTOR aberrations did not affect survival in the entire TCGA cohort, in both PIK3CA amplified and EGFR amplified HNSCC tumor subsets, there is a trend toward a shorter time to relapse in cases with RICTOR aberrations versus in those without." (PMID 31393061, 2019). "Nonetheless, we found that, as with AOA, CB-839 preferentially inhibits xenograft tumor growth of PIK3CA mutant, but not WT, CRC xenograft tumor growth." (PMID 31844152, 2019). "Western blots exhibited major downregulation of c-MYC protein upon C-KRAS-esiRNA and C-KRAS/PIK3CA-esiRNA treatment, but not C-PIK3CA-esiRNA treatment in DLD1 tumors, whereas HT29 tumor reacted to treatment in a different manner." (PMID 30001368, 2018). "Among tumor samples, ARID1A expression was negative in 27.3% of the tissues whereas cMET and PIK3CA expression was positive in 63.6% and 87.8% of the tumors respectively." (PMID 26334097, 2015). "The IC50 values for P7170 were in the broad range of 3 to 300 nM independent of either the genetic status of KRAS, PIK3CA, PTEN or the tumor sub-types." (PMID 25466244, 2014). "While NVP-BEZ235, a dual pan-PI3K and mTOR inhibitor, led to marked tumor regression in the PIK3CA-GEMM, it did not affect tumor growth significantly when treating the Kras-GEMM unless it was used in combination with a MEK inhibitor." (PMID 22666248, 2012).
tumor (continued). "In this study we observed that genes like PIK3CA and PTEN were expressed in tumor samples, but not at significantly different levels from normal colon tissue in both datasets." (PMID 21909432, 2011). "In vivo, induction of PIK3CA targeting shRNA, did not delay IPC298 tumor growth, compared to animals that were placed on sucrose." (PMID 19492075, 2009). "Consistent with in vitro proliferation and in vivo tumor growth data, knock-down of BRAF, MEK1/2, and PIK3CA in IPC298 cells did not delay cell cycle progression." (PMID 19492075, 2009). "In the HER2-negative cohort, one patient experienced a durable CR (23 weeks) and had a primary tumour with the following molecular characteristics: HER2 negative and EGFR negative; ER positive and PgR positive; low expression of PTEN and PIK3CA (E767K) SNP." (PMID 19844234, 2009). "However, in some cases, SNVs were seen only in the tumor and not in the corresponding CSF cfDNA, including SNVs in ROBO1, APC, PIK3CA or ARID1A." (PMID 37444642, 2023). "Furthermore, expanded genetic testing identified PIK3CA, AKT1, and PTEN alterations in 25% of the tumours originally classified as pathway non-altered." (PMID 35671774, 2022). "Five patients with PIK3CA mutant tumors were treated with the THP regimen, and four of them (80%) achieved pCR: three with a hormone-receptor-negative tumor, and one with a hormone-receptor-positive tumor." (PMID 35740668, 2022). "However, PIK3CA and p-AKT (T308) expression levels were not correlated with tumor prognosis in patients with ccRCC (P > 0.05)." (PMID 32547875, 2020). "Interestingly, viability of HAP1 cells did not seem to be affected by the knockout of known tumor type-specific oncogenes such as BCR, PIK3CA, KRAS, CTNNB1, or BRAF." (PMID 33228647, 2020). "Unlike PTEN-null BC, in PIK3CA-mutant BC the p110α isoform predominantly drives PI3K signalling instead of p110β, leading to investigation of PI3Kα inhibitors such as BYL719 as potential therapeutics for these tumours." (PMID 35582276, 2019). "Bioluminescence imaging of tumor xenografts stably expressing the PIK3CA sensor in PA1 and A2780 cells exhibited attenuating activity without any change in SKOV3 tumors expressing the PIK3CA sensor after cisplatin treatment." (PMID 23393606, 2013). "Indeed, many of the clinical studies have retrospectively analyzed pathway genetics sourced from archival or fresh tumor tissue (in particular, but not restricted to, PTEN and PIK3CA status)." (PMID 21317449, 2010). "Although a previous study reported worse outcomes in patients with early (stages II–III) PIK3CA-mutant CRC, the aggregate data do not currently suggest that KRAS- or PIK3CA-mutant tumours have distinctive clinical profiles or differential response to currently approved chemotherapy." (PMID 19603024, 2009). "In other words, tumor biology in mCRPC may not be as aggressive in a patient with only an AR amplification compared to those whose malignancy has multiple GAs that include AR (such as MYC, BRAF, PIK3CA, and others)." (PMID 38450313, 2023).
tumor (continued). "Moreover, in contrast to previous reports in HBC73–75, PIK3CA and other PI3Ks activating AKT as well as AKT1 and AKT3 were downregulated or not differentially expressed in tumours, suggesting that subtypes evaluated here are not likely to respond to therapies targeting PI3Ks and AKT inhibitors." (PMID 36220861, 2022).
cancer (2,192 papers, 2005 to 2026). A tumor composed of atypical neoplastic, often pleomorphic cells that invade other tissues. "PI3K, particularly the p110α catalytic isoform, is frequently mutated in cancer, and highly specific inhibitors such as alpelisib are currently used in oncology and in PIK3CA-related overgrowth disorders." (PMID 42196155, 2026). "These inhibitors exhibit significant antineoplastic properties and are being actively explored in cancer therapy, particularly in tumors with PIK3CA mutations." (PMID 40573322, 2025). "PIK3CA mutations, frequently involving hotspot single amino acid substitutions within the kinase domain, are recognized as oncogenic drivers in various cancers, including BC." (PMID 40050490, 2025). "Studies have demonstrated that mutations and aberrant activation of PIK3CA are associated with the progression of various cancers." (PMID 41142018, 2025). "For example, drugs like alpelisib (PIQRAY) have shown efficacy in PIK3CA-mutant cancers, including EC, making these mutations a potential biomarker for targeted therapy." (PMID 39858102, 2025). "A study evaluating 504 patients with diverse cancers found that KRAS mutations were present in 38% of patients with PIK3CA mutations compared with 16% of patients with wild-type PIK3CA (P = 0.001)." (PMID 39808497, 2025). "A large proportion of dispersed and clustered C>T mutations across various types of cancer have been attributed to A3B, particularly those affecting the phosphatidylinositol-4,5-bisphosphate 3-kinase catalytic subunit alpha gene (PIK3CA)." (PMID 40143363, 2025). "Among these variants, KRAS and PIK3CA have been previously reported as pathogenic somatic mutations in cancers." (PMID 41311737, 2025). "In cancers harbouring PIK3CA mutations or PTEN loss, PI3K/Akt-mTORC1 signalling is constitutively active." (PMID 40805230, 2025). "Activating mutations in PIK3CA, which encodes the catalytic p110α subunit of class IA phosphoinositide 3-kinases (PI3Ks), contribute to cancer pathogenesis by promoting cell growth, survival, motility, and glucose metabolism." (PMID 40724985, 2025). "PIK3CA mutations are prevalent in cancers that involve ectodermal or endodermal epithelia (e.g., endometrial and breast)." (PMID 40126231, 2025). "The cancer specifically acquired APOBEC3-context pathogenic mutations in PIK3CA (E545K) and RAD51C (P21S)." (PMID 40379787, 2025). "PIK3CA mutation was the most prevalent currently actionable mutation in all clinical stages affecting around 40% of cancers." (PMID 40421962, 2025). "This is also evident in the number of patients with diverse cancer diagnosis and different PIK3CA mutations that we investigated by several approaches." (PMID 41410746, 2025). "In EGFR-mutant cancer cells, an oncogenic mutation in the catalytic subunit alpha of phosphatidylinositol-4,5-bisphosphate 3-kinase (PIK3CA) was adequate to induce resistance to gefitinib, an EGFR inhibitor." (PMID 40342734, 2025). "Aberrant activity of this pathway, frequently due to mutations in genes such as PIK3CA, is associated with a range of diseases, including cancers, metabolic syndromes, and neurodegenerative disorders." (PMID 41424791, 2025). "PIK3CA, which encodes the p110α catalytic subunit, was first discovered to be frequently mutated in a variety of human cancers by a systematic sequencing of all 16 members of lipid kinases." (PMID 39717717, 2025).
cancer (continued). "As PIK3CA is the most frequently mutated oncogene in cancer and is fundamental for cancer development, researchers show prompting interest in targeting the PI3Kα for cancer therapy." (PMID 39717717, 2025). "PIK3CA mutations in cancer occur predominantly in exons 9 and 20, including H1047R, E545K, and E542K, which are called ‘‘hot-spot” mutations." (PMID 40055250, 2025). "Somatic mutations in the PIK3CA gene are commonly described in human cancers, such as colorectal cancer and lung cancer." (PMID 39980152, 2025). "Other notable mutated cancer-related genes include PIK3CA (7%), CREBBP (6%), KMT2C (6%), KMT2D (6%), RB1 (5%), PTEN (5%), and FAT1 (5%), all of which are reported as “Tier 1” cancer-related gene mutations in the COSMIC Cancer Gene Census21." (PMID 40057511, 2025). "Among these genes, PIK3CA, which encodes the p110α catalytic subunit, is the most frequently mutated gene in human cancers." (PMID 40050490, 2025). "Together, these findings are consistent with the presence of PIK3CA mutations at early stages of cancer development and align with previous observations that the mutational activation of PIK3CA is an early oncogenic event in UC60." (PMID 40846762, 2025). "PIK3CA mutations in cancer were first reported by Samuels and colleagues in 2004 in a small cohort of 35 colorectal cancer patients." (PMID 40508087, 2025). "Based on early cellular studies, common cancer-associated PIK3CA mutations such as PIK3CAH1047R are often regarded simply as “on” switches, or activators, of the pathway." (PMID 39706867, 2025). "Genes such as PIK3CA, FAT1, FAT4, and CTNNB1 exhibit relatively similar mutation frequencies across both cancers, though slightly higher in SC for PIK3CA and FAT1/FAT4." (PMID 41419500, 2025). "This study reports two unique TCRs against the PIK3CAN345K gene product, encoded by the 5th most common PIK3CA mutation, comprising 3% of all PIK3CA missense mutations, and is expressed in approximately 0.38% of all patients with advanced cancer." (PMID 41410746, 2025). "Recently, PIK3CA mutation-targeting drugs have become a new focus in the treatment of lung, breast, and other cancers." (PMID 40740763, 2025). "Somatic variants in the PIK3CA gene are among the most prevalent genetic alterations in various human cancers, including breast, colorectal, and cervical cancers, playing a critical role in oncogenesis." (PMID 41357804, 2025). "For instance, cancer cells harboring mutations in the PIK3CA gene or deletions in PTEN exhibited oncogenic activation of the PI3K/AKT/mTORC1 pathway, resulting in reduced sensitivity to lipid peroxidation and resistance to ferroptosis." (PMID 40066330, 2025). "These drugs also remain under investigation in further settings, particularly in cancers displaying PIK3CA mutations or PTEN loss." (PMID 40723241, 2025). "The selective PI3K inhibitor Alpelisib is being investigated to deter constitutive PIK3CA mutations in cancer." (PMID 40564017, 2025). "Secondly, PIK3CA mutation in cancer cells creates an immunosuppressive stromal environment by induction of high glycolysis, leading to rapid consumption of glucose and the production of lactate." (PMID 39717717, 2025).